DVL2 (dishevelled segment polarity protein 2)
Description:
Plays a role in the signal transduction pathways mediated by multiple Wnt genes. Participates both in canonical and non-canonical Wnt signaling by binding to the cytoplasmic C-terminus of frizzled family members and transducing the Wnt signal to down-stream effectors. Promotes internalization and degradation of frizzled proteins upon Wnt signaling.
Tractability: Small molecule: a structure with a bound ligand is known; it has a high-quality binding pocket. Antibody: UniProt places it where antibodies can reach, with medium confidence; its Gene Ontology location is reachable by antibodies, with medium confidence. PROTAC: UniProt records ubiquitination sites on it; ubiquitination databases record sites on it; its protein half-life has been measured; a small molecule that binds it is known.
Gene: Protein-coding gene on chromosome 17 (7,225,342 to 7,234,524, reverse strand). Ensembl gene ENSG00000004975.
Subcellular location: Cell membrane; Cytoplasm, cytosol; Cytoplasmic vesicle; Nucleus
Subcellular location (Human Protein Atlas): Nuclear bodies; Nucleoplasm; Aggresome
Pathways (Reactome):
Signal Transduction: Asymmetric localization of PCP proteins; Degradation of DVL; Disassembly of the destruction complex and recruitment of AXIN to the membrane; Negative regulation of TCF-dependent signaling by DVL-interacting proteins; PCP/CE pathway; RHO GTPases Activate Formins; Signaling by Hippo; TCF dependent signaling in response to WNT; WNT mediated activation of DVL; WNT5A-dependent internalization of FZD4
Vesicle-mediated transport: Cargo recognition for clathrin-mediated endocytosis; Clathrin-mediated endocytosis
Disease: WNT5:FZD7-mediated leishmania damping
Gene Ontology:
Molecular function: frizzled binding; identical protein binding; protein binding; protein domain specific binding; protein kinase binding; protein-macromolecule adaptor activity; small GTPase binding
Biological process: canonical Wnt signaling pathway; non-canonical Wnt signaling pathway; positive regulation of JNK cascade; positive regulation of transcription by RNA polymerase II; regulation of cell population proliferation; regulation of DNA-templated transcription; Wnt signaling pathway, planar cell polarity pathway; heart development; heart looping; neural tube closure; outflow tract morphogenesis; positive regulation of neuron projection arborization; regulation of actin cytoskeleton organization; segment specification; intracellular signal transduction; segmentation; small GTPase-mediated signal transduction; Wnt signaling pathway
Cellular component: cytoplasm; cytoplasmic vesicle; nucleus; clathrin-coated endocytic vesicle; cytosol; plasma membrane; apical part of cell; clathrin-coated vesicle; lateral plasma membrane
Genetic constraint (gnomAD): Loss-of-function variants: 38 observed, 69.31 expected, observed/expected ratio (o/e) 0.55, 90% interval 0.42 to 0.72. The upper end of that interval is the gene's LOEUF score, 0.72, which puts it in group 2 of 6, group 1 being the genes least tolerant of losing a copy. Missense variants: 931 observed, 1,023.3 expected, observed/expected ratio (o/e) 0.91, 90% interval 0.86 to 0.96. Synonymous variants: 428 observed, 398.66 expected, observed/expected ratio (o/e) 1.07, 90% interval 0.99 to 1.16.
Homologues: Orthologues: chimpanzee DVL2 (100% identical), macaque DVL2 (99% identical), dog DVL2 (97% identical), mouse Dvl2 (97% identical), guinea pig DVL2 (96% identical), rat Dvl2 (96% identical), rabbit DVL2 (92% identical), pig DVL2 (91% identical), tropical clawed frog dvl2 (77% identical), zebrafish dvl2 (74% identical), Drosophila melanogaster dsh (39% identical), Caenorhabditis elegans dsh-1 (35% identical), and 2 more. Paralogues in human: DVL3 (68% identical), DVL1 (58% identical), DIXDC1 (14% identical).
Diseases named in the same sentence as DVL2 in open-access papers:
DVL2 is named in the same sentence as 77 diseases in open-access papers, as found by Europe PMC text mining. Sharing a sentence is not in itself a finding about the gene and the disease. The quoted sentences say what the papers report.
colorectal cancer (18 papers, 2011 to 2025). A primary or metastatic malignant neoplasm that affects the colon or rectum. "We examined the possibility that DDX3 could be associated with phosphorylation of Dvl2 and nuclear β-catenin expression in colorectal cancer." (PMID 26892600, 2016). "In particular, Vangl2 has been shown to promote the migration and invasion of colorectal cancer cells by activating the fibronectin/integrin β1/FAK signaling cascade through DVL2." (PMID 41425715, 2025). "In colorectal cancer, upregulation of Dvl2 and Dvl3, enhancing Wnt signaling, promotes metastasis progression." (PMID 40569965, 2025). "Recently, it was discovered that DCDC2 plays a role in the progression of colorectal cancer by interacting with DVL2 to regulate the Wnt pathway." (PMID 40533767, 2025). "WNT and NF-κB signaling through TNFR regulation also promote colorectal cancer progression in a mode coordinated by Disheveled segment polarity protein 2 (DVL2)." (PMID 39354505, 2024). "Accumulation of DVL-2 in the nucleus has been shown to result in hyper-activation of Wnt signaling in colorectal cancer." (PMID 34659647, 2021). "On the other hand, in colorectal cancer, autophagy drives the degradation of β-catenin and Dishevelled2 (DVL2) proteins, thus hampering Wnt/β-catenin induced EMT." (PMID 34944948, 2021). "Genetic deletion of Dvl2 reduced the intestinal tumor numbers in a dose-dependent way in the Apc(Min) model for colorectal cancer." (PMID 27833078, 2016). "Overexpression of the Dvl2 protein results in potent activation of β-catenin/TCF signaling in colorectal cancer." (PMID 26892600, 2016). "In the present study, DDX3-mediated β-catenin activation occurred through the CK1ε/Dvl2 axis and, in turn, promoted tumor invasion and poor prognosis in colorectal cancer patients." (PMID 26892600, 2016). "It has been reported that niclosamide downregulates components of the Wnt pathway, specifically cytosolic Dvl2 expression, resulting in diminished downstream Wnt/β-catenin signaling in colorectal cancers." (PMID 22195040, 2011). "Tanksleyet al. demonstrated that NEDD4L suppresses colorectal cancer by ubiquitylating DVL2." (PMID 35593463, 2022). "Suppression of Dvl2 increased cisplatin sensitivity via inhibition of the Wnt/β-catenin pathway in lung cancer cells, and blocking Dvl2/Snail signaling suppressed metastasis and reversed chemoresistance in colorectal cancer cells." (PMID 35965516, 2022). "Upregulation of Dvl sustains Wnt/β-catenin signaling, whereas Dvl2 loss suppresses tumor development in the intestine of the APC-mutant mouse, suggesting Dvl2 may represent a potential target for colorectal cancer therapy." (PMID 30866999, 2019). "Therefore, Dvl2 phosphorylation by CK1ε and/or DDX3 would appear to play a central role in cytoplasmic β-catenin accumulation and its nuclear translocation, and consequently in the promotion of tumor invasion in colorectal cancer patients." (PMID 26892600, 2016).
breast cancer (17 papers, 2007 to 2025). A primary or metastatic malignant neoplasm involving the breast. "Wnt5a promotes breast cancer cell migration via Dishevelled 2 (Dvl2)/Dishevelled-associated activator of morphogenesis 1 (Daam1)/RhoA signaling pathway." (PMID 28289332, 2017). "While DVL2 expression in baseline biopsy tissues didn’t significantly correlate with recorded clinic-pathological variables of breast cancer, a trend of significant positive correlations was observed between DVL2 and multiple clinical markers of high-risk breast cancer namely age, −stage>N1, NLR." (PMID 36809986, 2023). "The present study reports DVL2 association with CD8α levels in HER2+ breast cancer biopsy tissues." (PMID 36809986, 2023). "Herein, we investigated the DVL2 association with genes involved in antigen presentation and T cell maintenance in HER2+ breast cancer cell lines." (PMID 36809986, 2023). "Stimulation of breast cancer cell lines with Wnt5a-conditioned media enhances cellular migration and robustly increases phosphorylation of Dvl2 compared to vector control-conditioned media." (PMID 37147680, 2023). "NAC is frequently used for early and advanced stage breast cancer patients, and our study demonstrates that high DVL2 is found in biopsy tissue before the NAC and high CD8α levels are found in biopsy tissues post NAC." (PMID 36809986, 2023). "Next, we found significantly higher DVL2 protein expression in the same cohort in different molecular subtypes of breast cancer: Luminal (n = 64), HER2+ (n = 10), TNBC (n = 16) compared to normal breast tissue (n = 18) (p < 0.0001)." (PMID 36809986, 2023). "Consistent with findings from mammalian development, Wnt5a stimulation phosphorylates Vangl2 at critical functional residues across a panel of breast cancer cell lines and loss of VANGL2 suppresses Dvl2 phosphorylation." (PMID 37147680, 2023). "Breast cancer cells overexpressing Vangl1 or Vangl2 exhibit increased motility and Dvl2 phosphorylation compared to cells transduced with control lentivirus and display a distinctive hyper-protrusive leading-edge morphology." (PMID 37147680, 2023). "Our study is noteworthy since examining the crosstalk between the Wnt and HER2 pathways presents novel insight into the possible immune regulatory role of DVL2 proteins in HER2+ breast cancer." (PMID 36809986, 2023). "For instance, recent data have indicated that USP9X promotes the activation of canonical Wnt signaling through deubiquitinating and stabilizing DVL2 in breast cancer cells." (PMID 37726816, 2023). "In this section, we aim to critically investigate the role of DVL2 depletion in regulating key proteins of EGFR signaling cascade with or without HER2 inhibition in two different in vitro models of HER2+ breast cancer." (PMID 36809986, 2023). "In this study, we used the UALCAN analysis to emphasize the differential expression of DVL2 in different molecular subtypes of breast cancer and observed that DVL2 is upregulated in the breast tumor samples compared to the benign breast tissues." (PMID 36809986, 2023). "Next, we performed Spearman’s rank correlation analyses between DVL2 expression and multiple clinical and prognostic indicator of breast cancer survival." (PMID 36809986, 2023). "Rac1 is reported to be essential for Wnt-driven expansion and transformation of intestinal stem cells and Wnt5a promotes breast cancer cell migration via the Dvl2/Rab35/Rac1 signaling pathway." (PMID 24962779, 2014). "Taken together, we demonstrated for the first time that Wnt5a promotes breast cancer cell migration via Dvl2/Daam1/RhoA." (PMID 22655072, 2012). "In this study, we demonstrated that Wnt5a promotes MDA-MB-231 breast cancer cell migration by activating Dvl2/Daam1." (PMID 22655072, 2012). "We showed here that Wnt5a activated Dvl2, Daam1 and RhoA, and promoted migration of breast cancer cells, which was, however, abolished by Secreted Frizzled-related protein 2 (sFRP2) pretreatment." (PMID 22655072, 2012).
breast cancer (continued). "In summary, we presented the first direct evidence that Wnt5a promotes breast cancer cell migration via Dvl2/Daam1/RhoA." (PMID 22655072, 2012). "DVL1 and DVL3 were consistently expressed at relatively uniform levels in all the breast cancer cell lines, whereas DVL2 was expressed in a more differential manner." (PMID 17897439, 2007). "DVL2 expression is negatively correlated with the presence of cytotoxic immune cells in the TME suggesting that DVL2 might serve as a prognostic biomarker in HER2+ breast cancer." (PMID 36809986, 2023). "Next, to further investigate the immunoregulatory and prognostic role of DVL2 in response to NAC, we performed a subgroup analysis between DVL2 and different clinical and/or prognostic markers of breast cancer in biopsy and resection specimens of patients who received NAC." (PMID 36809986, 2023). "In addition to the promising staining results, we examined the correlation between DVL2 and prominent clinical predictors of breast cancer in patients who received NAC (before and after)." (PMID 36809986, 2023). "Interestingly, DVL2 protein levels were significantly higher in all subtypes of breast cancer compared to benignbreast tissues and the highest expression levels were found in HER2+ tumors compared to other subtypes of breast cancer, Luminal and TNBC." (PMID 36809986, 2023). "Remarkably, we observed that high DVL2 expression was significantly associated with both poor OS and DMFS with a hazard ratio of 1.87 and 2.12 (p < 0.0001) in 276 HER2-amplified breast cancer patient cohort indicating potential prognostic role of DVL2 in HER2+ breast cancer patients." (PMID 36809986, 2023). "While we identified some novel thought-provoking associations between DVL2 and multiple clinical prognostic indicators of breast cancer survival, we failed to observe these correlations in HER2+ patients who didn’t receive NAC." (PMID 36809986, 2023). "Hence, we aim to understand the differential expression of DVL2 protein in different molecular subtypes of breast cancer." (PMID 36809986, 2023). "Further subgroup analyses revealed a significant negative correlation between baseline TIL score and age (p < 0.05) as well as baseline CD8α levels and N-stage> 1 (p < 0.05) denoting possible association between DVL2 and immune-regulatory markers of HER2+ breast cancer." (PMID 36809986, 2023). "Using Kaplan Meier survival curves, we compared whether high and low expression levels of DVL2 have any association with overall survival (OS) and distant metastases-free survival (DMFS) in HER2+ breast cancer patients." (PMID 36809986, 2023). "Since it is known that ROR1/2 signaling, especially after stimulation with Wnt5a, requires Dvl for signal transduction, we aimed to analyze which of the Dvl proteins (Dvl1, Dvl2 or Dvl3) might be a good marker for active ROR signaling in breast cancer." (PMID 26862065, 2016). "Whether Dvl1 and Dvl3, homologs of Dvl2, induce the migration of breast cancer cells needs to be further studied." (PMID 22655072, 2012). "Constitutively active ΔDAD-Daam1 induced RhoA activation, the formation of stress fibers, and migration of MCF-7 cells, indicating that Daam1 may be specifically required for the activation of Dvl2 after Wnt5a treatment in breast cancer cells." (PMID 22655072, 2012). "We also used siRNA to knock down Dvl2 expression in breast cancer cells and checked whether Wnt5a-induced cell migration could be inhibited." (PMID 22655072, 2012). "To test whether Dvl2 is also involved in niclosamide-induced Wnt/β-catenin signaling inhibition in prostate and breast cancer cells, we examined both total cellular and cytosolic levels of Dvl2 expression." (PMID 22195040, 2011). "However, there is a lack of literature delineating mechanistic association of DVL2 in HER2+ breast cancer." (PMID 36809986, 2023).
breast cancer (continued). "This reveals another aspect that DVL2 might act as a predictor of prognostic biomarkers specifically in aggressive HER2+ breast cancer which would require further future analysis in a larger cohort of breast cancer patients." (PMID 36809986, 2023). "We next examined whether RhoA was downstream of Dvl2 in human breast cancer cells." (PMID 22655072, 2012). "We identified DVL2 nuclear localization via immune staining and sub-cellular fractionation in two different HER2+ breast cancer cell lines." (PMID 36809986, 2023). "Findings from these studies clearly demonstrate the promising combinatorial anti-proliferative role of DVL2 and HER2 silencing in HER2+ breast cancer." (PMID 36809986, 2023). "This study aimed to uncover the novel interaction between DVL2 and HER2-positive (HER2+) breast cancer (BC) in regulating tumor immunity and disease progression." (PMID 36809986, 2023). "Using CPTAC breast cancer data cohort from UALCAN analysis platform, we confirmed that the expression of DVL2 in primary breast tumor samples (n = 125) was significantly higher than that in benign breast tissues (n = 18) (p < 0.0001)." (PMID 36809986, 2023). "WWP1-mediated ubiquitination of DVL2 initiates the WNT-PCP pathway, resulting in cell motility and breast cancer invasion/metastasis." (PMID 34712671, 2021). "In breast cancer cell models, bardoxolone methyl treatment led to significant depletion of phosphorylated LRP6 and phosphorylated Disheveled 2 (DVL2), alongside suppression of cytoplasmic β-catenin activation, resulting in the downregulation of Wnt target genes and cancer stem cell (CSC) markers." (PMID 40732256, 2025). "Next, we determined whether DVL2 binds to the promoter regions of genes involved in antigen presentation (HLA-A, HLA-C) and T-cell maintenance (STAT1, STAT6, TGFB1) in HER2-positive breast cancer cells." (PMID 36809986, 2023). "Additionally, CD8α levels were negatively correlated with NLR (rho = − 0.59; p = 0.030) denoting probable crosstalk between DVL2 and CD8α proteins in predicting prognostic outcomes of HER2+ breast cancer." (PMID 36809986, 2023). "In summary, this report examines the novel link between DVL2 and TILs in HER2+ breast cancer." (PMID 36809986, 2023). "As shown here, CDK3 exhibited a potent inhibitory effect on Wnt signaling in breast cancer cells through regulating the phosphorylation level of LRP6, the expression of Axin1 and Dvl2, leading to the inhibition of β-catenin, and this process is possibly due to decreased expression of Wnt3a." (PMID 29156693, 2017). "To further validate our in vitro analyses of DVL2 role in HER2+ breast cancer, we performed TIL-scoring and mapped DVL2 and CD8α protein levels via immune staining in a preliminary sample of 24 HER2+ breast cancer patients at baseline biopsy (N = 24) and post NAC resection (N = 14) tissues." (PMID 36809986, 2023). "However, no significant changes of DVL2 protein expression were found across different subtypes of breast cancer in a separate subgroup analysis between Luminal, HER2+ and TNBC." (PMID 36809986, 2023). "Thus, Wnt5a-dependent migration and Dvl2 phosphorylation in breast cancer cells is driven by engagement of a non-canonical Wnt signaling pathway rather than canonical Wnt signaling." (PMID 37147680, 2023). "We found that up-regulation of KIF3B activates the Wnt signaling via increasing the expression of Dvl2, p-GSK-3βser9, total and nucleus β-catenin, then up-regulation of Wnt signaling target genes such as CyclinD1, C-myc and MMP-7, which are highly expressed in breast cancer." (PMID 33542902, 2020). "Similarly, DVL2 positively correlates with NLR, while a negative correlation was found between DVL2 and CD8α, and in between CD8α and post NAC TIL score, suggesting an association between DVL2 and TIL score in HER2+ breast cancer." (PMID 36809986, 2023).
breast cancer (continued). "Furthermore, we found that silencing of KIF3B decreased the expression of Dvl2, phospho-GSK-3β, total and nucleus β-catenin, then subsequent down-regulation of Wnt/β-catenin signaling target genes such as CyclinD1, C-myc, MMP-2, MMP-7 and MMP-9 in breast cancer cells." (PMID 33542902, 2020).